IL4R (interleukin 4 receptor)
Diseases named in the same sentence as IL4R in open-access papers (continued):
Sharing a sentence is not in itself a finding about the gene and the disease.
cryptococcal infection (2 papers, 2014 to 2021). "Taken together, typical features of Th2-related susceptibility can be found early in cryptococcal infection and accompany the early beneficial activity of IL-4Rα signaling." (PMID 24475277, 2014). "This is noteworthy and contrary to our pulmonary cryptococcosis model where IL-4Rα−/− mice are completely resistant against C. neoformans even over a long period of time (i.e. >200 dpi)." (PMID 24475277, 2014). "We therefore hypothesize that latent pulmonary infection, as observed in IL-4Rα-/- mice and hypothesized in healthy individuals evidenced by reactivation of dormant cryptococcal infection, is sufficient to trigger basal production of anti-cryptococcal IgG and IgM antibodies." (PMID 34367172, 2021). "Corroborating the data from HIV-negative CM patients, cryptococcal infection of WT and IL-4Rα-/- mice led to an increase in anti-cryptococcal IgG, but not IgM production, consistent with a previously published study." (PMID 34367172, 2021). "Interestingly, titers of anti-cryptococcal IgG were significantly higher in WT mice, developing disseminated cryptococcal disease and high fungal burden in the lung, compared to IL-4Rα-/- mice, exhibiting a latent pulmonary cryptococcal infection without overt disease." (PMID 34367172, 2021).
diabetes (2 papers, 2009 to 2021). "Several studies have reported that the interactions of the IL-4 and IL-4R genotypes are associated with diabetes, cancer, and pemphigus foliaceus in humans." (PMID 33920608, 2021).
emphysema (2 papers, 2006 to 2023). "Furthermore, TSK/+ mice exhibiting disrupted genes encoding IL-4Rα, TGF-β, or IL-4 lacked skin sclerosis but developed emphysema, indicating that different genes are involved in the development of skin sclerosis and pulmonary emphysema in TSK/+ mice." (PMID 17049072, 2006).
endometriosis (2 papers, 2022 to 2025). The growth of functional endometrial tissue in anatomic sites outside the uterine body. "Additionally, our findings revealed that the expression of the macrophage receptor IL-4R was upregulated after obtaining the exosome of the endometriosis intervention." (PMID 36551866, 2022). "Using machine learning algorithms, five key genes were selected in the endometriosis: BST2, IL4R, INHBA, PTGER2, and MET." (PMID 40405976, 2025).
fungal infection (2 papers, 2011 to 2025). "Arg1 induction upon fungal infection was partially dependent on the IL-4Rα/STAT6 signaling axis." (PMID 21246055, 2011).
gallbladder carcinoma (2 papers, 2014 to 2022). "Taken together, in human gallbladder carcinoma tissue, we found a statistically significant association between the expression IL4R and IL13Rα1 and poor prognostic properties by analyzing tissue microarray." (PMID 35207737, 2022). "The Cy-IL4Rα-positivity predicted a 1.895-fold (95% CI; 1.092–3.288) greater risk of death and a 2.048-fold (95% CI; 1.183–3.548) greater risk of relapse or death of gallbladder carcinoma patients." (PMID 35207737, 2022). "In survival analysis of gallbladder carcinoma patients, another interesting finding of this study is that nuclear localization of IL4Rα was presented as an independent indicator of shorter survival of gallbladder carcinoma patients." (PMID 35207737, 2022). "This study also presented that nuclear expression of IL4Rα and IL13Rα1 was involved in pathogenesis important in the progression of gallbladder carcinomas." (PMID 35207737, 2022). "This study evaluated the expressions of IL4Rα and IL13Rα1 in human gallbladder carcinomas and presented IL4Rα/IL13Rα1 pathway is involved in the progression of gallbladder carcinomas." (PMID 35207737, 2022). "The positivity of nuclear expression of IL4Rα was presented as an independent indicator of shorter survival gallbladder carcinoma patients." (PMID 35207737, 2022). "In conclusion, this study showed the expression of IL4Rα and IL13Rα1 was used as a potential prognostic marker of gallbladder carcinomas and presented nuclear expression of IL4Rα as an independent indicator of shorter OS and FRS." (PMID 35207737, 2022). "This prognostic significance of Nu-IL4Rα-positivity presents the expression pattern of IL4Rα and IL13Rα1 is used as prognostic indicators of gallbladder carcinoma patients." (PMID 35207737, 2022). "In univariate survival analysis, nuclear or cytoplasmic expressions of IL4Rα and IL13Rα1 were significantly associated with shorter OS and RFS of gallbladder carcinoma patients." (PMID 35207737, 2022). "We demonstrated that the downregulated IL4Rα or IL13Rα1 caused apoptosis in SNU308 gallbladder cells and investigated the anti-carcinogenic effect of AZD1480, a JAK2 inhibitor, in human gallbladder carcinoma SNU308 cells." (PMID 35207737, 2022). "Immunohistochemically, IL4Rα and IL13Rα1 were expressed in cytoplasm and nuclei of gallbladder cancer cells." (PMID 35207737, 2022). "Therefore, the result of this study suggests the expressions of IL4Rα and IL13Rα1 as novel prognostic indicators of gallbladder carcinoma patients." (PMID 35207737, 2022). "However, the expressions of IL4Rα and IL13Rα1 were dominant on cytoplasm and nuclei in gallbladder cancer cells." (PMID 35207737, 2022). "However, the role of IL4Rα and IL13Rα1 signaling pathway has not been fully understood in the development of gallbladder cancer." (PMID 35207737, 2022). "The potential prognostic clinicopathologic factors and the expressions of Nu-IL4Rα, Cy-IL4Rα, Nu-IL13Rα1, and Cy-IL13Rα1 were evaluated for their impact on OS and RFS of gallbladder carcinoma patients." (PMID 35207737, 2022). "After knockdown of IL4Rα or IL13Rα1, cell assays to measure the proliferation and apoptosis and Western blotting analysis were conducted in SNU308 human gallbladder cancer cells." (PMID 35207737, 2022). "On the other hand, it was also confirmed that gallbladder carcinoma cell lines (TGBC-1-TKB and TGBC-44-TKB) and extrahepatic cholangiocarcinoma cell lines (KMBC and Sk-ChA-1) expressed IL-4Rα, although the expression levels were lower than those of CCKS-1 and KKU-100 cells." (PMID 24868471, 2014). "However, the exact effects of IL4Rα or IL13Rα1 in gallbladder cancer development have not been studied." (PMID 35207737, 2022). "Therefore, our findings suggests that the IL4Rα and IL13Rα1 complex and JAK2 signaling pathway could be efficient therapeutic targets for gallbladder cancer treatment." (PMID 35207737, 2022).
gallbladder carcinoma (continued). "Especially, the gallbladder carcinoma patients Nu-IL4Rα-positive tumors had a 3.379-fold (95% CI; 1.825–6.254) greater risk in OS analysis and a 2.919-fold (95% CI; 1.622–5.253) greater risk in RFS analysis compared with the patients with negative for Nu-IL4Rα." (PMID 35207737, 2022).
head–neck carcinomas (2 papers, 2020 to 2022). "The overexpression of IL-4Rα in tumor cells is usually associated with poor prognosis in some human cancer (bladder, head–neck carcinomas, etc.), suggesting that IL-4Rα-targeted therapy would be appropriate for advanced/stage tumors." (PMID 33233582, 2020).
heart failure (2 papers, 2017). Inability of the heart to pump blood at an adequate rate to meet tissue metabolic requirements. "We found that the interleukin‐13 receptor α1 is present in the myocardium and, together with the complementary type‐2 interleukin‐4 receptor chain Il4ra, is significantly downregulated in the hearts of patients with heart failure." (PMID 28528324, 2017).
intestinal tumor (2 papers, 2016 to 2022). "In the AOM/DSS model of tumorigenesis, signaling through IL-4 receptor α (IL-4Rα) promoted intestinal tumor growth." (PMID 27148488, 2016).
ischemia (2 papers, 2011 to 2023). A hypoperfusion of the BLOOD through an organ or tissue caused by a PATHOLOGIC CONSTRICTION or obstruction of its BLOOD VESSELS, or an absence of BLOOD CIRCULATION. "Interleukin 4 receptor alpha chain (IL-4Ra) is expressed in neurons and plays a critical role in modulating neuronal death through activation of signal transducer and activator of transcription 6 (STAT6) during ischemia." (PMID 36782269, 2023).
ischemic stroke (2 papers, 2011 to 2024). A stroke disorder caused by obstruction of blood flow to the brain, due to thrombotic (local blood clot formation) or embolic (due to a blood clot or other material traveling from another site) event. "In conclusion, using GPIbα/IL4Rα mice, we demonstrated the crucial role for GPIbα in ischemic stroke." (PMID 21914206, 2011).
keloid (2 papers, 2020 to 2023). An irregularly shaped, elevated mark on the skin caused by deposits of excessive amounts of collagen during wound healing. "Our results associate keloid tissues with an inflammatory milieu representing multiple T-helper pathways, including the Th2 (e.g. IL-4R, CCL11, TSLP, TNFSF4/OX40L, TNFRSF4/OX40), Th1 (e.g. IFNγ, CXCL10/11), Th17/Th22 (e.g. PI3, CCL20, S100As) axes, as well as the JAK/STAT signaling molecule JAK3." (PMID 33329590, 2020). "We observed increased cellular infiltrates in keloid tissues, including T-cells, dendritic cells, mast cells, as well as greater IL-4rα+, CCR9+, and periostin+ immunostaining." (PMID 33329590, 2020). "Supporting our mRNA expression data, we noted increased IL-4Rα+ immunostaining in both lesional and non-lesional keloid skin as compared to normal skin (P<0.05 for lesional versus non-lesional skin comparison)." (PMID 33329590, 2020).
lung fibrosis (2 papers, 2018 to 2019). "According to our previous results, in chronic EAA patients IL-4Rα BALF concentrations were positively correlated with the extent of lung fibrosis on HRCT." (PMID 30911386, 2019). "Therefore, we can conclude that IL-4Rα responsive B cells are required to down-regulate granulomatous pathology and lung fibrosis during synchronous S. mansoni egg challenge." (PMID 30619289, 2018).
lupus (2 papers, 2018 to 2024). "The study shows that rare, damaging variants in lupus patients enable breach of B cell immune tolerance checkpoints and suggests involvement for dysregulated IL-4R signaling and BAFF-R expression." (PMID 38417019, 2024).
Macrothrombocytopenia (2 papers, 2019 to 2023). "IL4R/GPIbα mice are GPIbα-deficient mice without the associated macrothrombocytopenia; however, we found that during melioidosis, platelet counts were still reduced in IL4R/GPIbα mice compared with controls." (PMID 30312422, 2019).
mesothelioma (2 papers, 2009 to 2021). A usually malignant and aggressive neoplasm of the mesothelium which is often associated with exposure to asbestos. "Higher expression of mRNA and protein of IL4Rα was associated with shorter survival of mesothelioma patients." (PMID 33419470, 2021). "Immunohistochemistry studies have also shown high expression levels of interleukin-4 receptor (IL-4R) on patient mesothelioma samples." (PMID 19755995, 2009).
osteosarcoma (2 papers, 2016 to 2021). A usually aggressive malignant bone-forming mesenchymal neoplasm, predominantly affecting adolescents and young adults. "Similarly, inhibition of JAK2, which is downstream of IL4R, delayed tumor growth in an osteosarcoma xenograft model." (PMID 33419470, 2021).
papilloma (2 papers, 2013 to 2016). A benign epithelial neoplasm that projects above the surrounding epithelial surface and consists of villous or arborescent outgrowths of fibrovascular stroma. "The incidence of papillomas was increased in IL-4Rα−/− mice when compared to littermate control IL-4Rα+/− mice and to all other experimental groups." (PMID 24403255, 2013). "A similar, perhaps less pronounced increase in papilloma incidence was observed for IL-13−/− mice as had been observed for IL-4Rα−/− mice, suggesting that IL-13 signaling via IL-4Rα is responsible for the protective effect." (PMID 24403255, 2013). "Because we detected an increase in papilloma incidence in IL-4Rα−/− compared to IL-4−/− mice, we reasoned that IL-13 as the second ligand for IL-4Rα might have been responsible for this difference." (PMID 24403255, 2013). "This experiment showed that even in the absence of T cells or B cells, the difference in papilloma incidence between IL-4Rα-deficient and IL-4Rα-competent animals was retained although differences were less pronounced." (PMID 24403255, 2013). "To this end, we compared papilloma incidence between RAG2−/−/IL-4Rα−/− double-knockout mice and RAG2−/−/IL-4Rα+/− mice as well as papilloma incidence between RAG2−/−/IL-4Rα−/− mice and RAG2+/+/IL-4Rα−/− mice after DMBA/TPA treatment." (PMID 24403255, 2013). "Next, we examined if absence of T cells or B cells affected papilloma incidence with regard to the presence of IL-4Rα." (PMID 24403255, 2013). "The fact that RAG2−/−/IL-4Rα−/− double-knockout mice and RAG2+/+/IL-4Rα−/− both showed increased papilloma incidence suggests that IL-13 signaling neither in T cells, nor in B cells was the main reason for enhanced papilloma incidence." (PMID 24403255, 2013). "A second independent experiment comparing IL-4Rα−/−, IL-4−/−, IFN-γ−/−, and wild-type BALB/c mice showed the same result, namely an increased papilloma incidence in IL-4Rα−/− mice (data not shown)." (PMID 24403255, 2013). "We found that IL-4Rα−/− but not IL-4−/− mice have enhanced papilloma formation, suggesting that IL-13 may be involved." (PMID 24403255, 2013).
periodontal disease (2 papers, 2019 to 2021). "Among common oral inflammatory conditions, the presence of epigenetic modifications in proinflammatory cytokines such as Fas-associated death domain protein (FADD), interleukin-12 subunit beta (IL-12B), and interleukin-4 receptor (IL-4R) has been associated with periodontal disease." (PMID 34370052, 2021).
pneumonia (2 papers, 2021 to 2025). An acute, acute and chronic, or chronic inflammation focally or diffusely affecting the lung parenchyma, caused by an infection in one or both of the lungs (by bacteria, viruses, fungi, or mycoplasma.). "Research indicates that the BL13 acupoint modulates pneumonia by targeting multiple genes, such as FCER2, IL4R, FASLG, and others, to modulate cytokine signaling in the immune system." (PMID 40098935, 2025).
renal carcinoma (2 papers, 2016). A carcinoma arising from the epithelium of the renal parenchyma or the renal pelvis. "We also confirmed that IL-4Rα expression was increased in renal cancer tissues compared with that in adjacent normal cancer tissues." (PMID 27895317, 2016). "In addition, we showed that IL-4Rα protein was upregulated in renal cancer tissues compared to that in adjacent normal tissues." (PMID 27895317, 2016).
rubella (2 papers, 2010 to 2011). A viral infection caused by the rubella virus. "While the univariate tests implicated SNPs in the LTA, IL6 and IL4R genes, the analysis of all SNPs identified not only these genes but also a broader collection of genes that appear to contribute to variation in rubella antibody levels." (PMID 20923569, 2010).
skin cancer (2 papers, 2011 to 2025). "Mice lacking IL-4Rα showed earlier skin tumor onset and higher tumor counts over time compared with mice with intact IL-4Rα, regardless of TSLP expression." (PMID 39744942, 2025).
skin infection (2 papers, 2011 to 2016). An inflammatory process affecting the skin, caused by bacteria, viruses, parasites, or fungi. "DEC recovered from 4xIL-4Rα−/− mice contained only a smallSiglecF+ eosinophil population compared to 4x WT mice(p<0.05),demonstrating that IL-4Rα expression is critical for mediating the influx ofeosinophils into the 4x skin infection site." (PMID 21445234, 2011). "However, whilst the absence of IL-4Rα resulted in increased numbers of CD4+ cells in the skin infection site and the sdLN, the cells in the sdLN remained hypo-responsive in vivo to stimulation with parasite antigen similar to 4x WT mice." (PMID 27505056, 2016). "Indeed, in the absence of IL-4Rα signaling, significantly greater numbers of CD3+CD4+ T cells were present in the skin infection site of 4x IL-4RαKO, compared to 4x WT mice (p<0.0001)." (PMID 27505056, 2016).
Sm (2 papers, 2018 to 2025). "IL-4Rα expression by Foxp3+ Treg cells was further enhanced following Sm infection, suggesting a strong requirement for this receptor either to preserve Treg cell activity or foster their transdifferentiation into ex-Foxp3 Th2 cells." (PMID 30379806, 2018). "CD4+ Foxp3+ Treg cells expressed IL-4Rα under a steady state and up-regulated their expression upon Sm infection." (PMID 30379806, 2018). "Indeed, additional germline variants in KIT and in genes encoding for cytokines or their receptors (e.g., IL13, IL6, IL6R, IL31, IL4R), as well as increased copy numbers of the TPSAB1 gene encoding for α‐tryptase, have been increasingly recognized as associated with systemic mastocytosis in adults." (PMID 41177946, 2025).
soft tissue sarcoma (2 papers, 2021 to 2022). A malignant neoplasm arising from muscle tissue, adipose tissue, blood vessels, fibrous tissue, or other supportive tissues excluding the bones. "In human soft-tissue sarcomas, immunohistochemical expression of IL4Rα was significantly associated with IL13Rα1 expression." (PMID 33419470, 2021). "Nuclear and cytoplasmic expression of IL4Rα and IL13Rα1 were significantly associated with shorter survival of soft-tissue sarcoma patients in univariate analysis." (PMID 33419470, 2021). "This study suggests IL4Rα and IL13Rα1 are associated with the progression of soft-tissue sarcoma, and the expression of IL4Rα and IL13Rα1 might be novel prognostic indicators of soft-tissue sarcoma patients." (PMID 33419470, 2021). "The poor prognosis of the patients having a tumor with higher expression of IL4Rα has been reported in renal cell carcinoma, malignant mesothelioma, and soft tissue sarcomas." (PMID 35207737, 2022). "This study investigated the immunohistochemical expression of IL4Rα and IL13Rα1 in 89 soft-tissue sarcomas of the extremities, superficial trunk, and retroperitoneum." (PMID 33419470, 2021). "Multivariate analysis indicated that nuclear expression of IL4Rα and IL13Rα1 were independent indicators of shorter overall survival (IL4Rα; p = 0.002, IL13Rα1; p = 0.016) and relapse-free survival (IL4Rα; p = 0.022, IL13Rα1; p < 0.001) of soft-tissue sarcoma patients." (PMID 33419470, 2021). "Moreover, the co-expression pattern of nuclear IL4Rα and IL13Rα1 was an independent indicator of shorter survival of soft-tissue sarcoma patients (overall survival; overall p < 0.001, relapse-free survival; overall p < 0.001)." (PMID 33419470, 2021). "However, studies on IL4Rα and IL13Rα1 in soft-tissue sarcomas have been limited." (PMID 33419470, 2021). "Furthermore, in a previous study evaluated for the prognostic significance of the expressions of IL4Rα and IL13Rα1 according to their subcellular localization, both nuclear expressions of IL4Rα and IL13Rα1 were the independent indicators of shorter OS and RFS of soft tissue sarcoma patients." (PMID 35207737, 2022).
thyroid cancer (2 papers, 2019 to 2022). "A number of studies have reported the expression of IL4R in all types of thyroid cancers." (PMID 36009525, 2022). "Various types of thyroid cancers, namely, papillary, follicular, and anaplastic, express IL-4R." (PMID 36009525, 2022). "The expression of IL4Rα was analyzed in the human thyroid cancer cell line Cal-62." (PMID 36009525, 2022). "However, to our knowledge, currently, antitumor therapies have not targeted IL4R to treat thyroid cancers." (PMID 36009525, 2022).
type 1 diabetes (2 papers, 2022). "In this study, we used single-cell sequencing for the first time in the world to reveal that IL4R expression is upregulated in the Tregs of patients with type 1 diabetes." (PMID 35626661, 2022).
acute lymphoblastic leukemia (1 paper, 2015). Leukemia with an acute onset, characterized by the presence of lymphoblasts in the bone marrow and the peripheral blood. "Furthermore, the genes encoding IFN-γ, GM-CSF, IL-4, IL-8, IL-2Rα, IL-2Rβ, IL-4R, IL-12Rβ, chemokines, chemokine receptors, and TNF were highly expressed in CIK cells under stimulation by acute lymphoblastic leukemia (ALL) cells." (PMID 25962508, 2015).